PIEZO1 (piezo type mechanosensitive ion channel component 1 (Er blood group))
Diseases named in the same sentence as PIEZO1 in open-access papers (continued):
Sharing a sentence is not in itself a finding about the gene and the disease.
cancer (continued). "Our paper is a review of the latest literature on the role of the Piezo1 and TRP families in the molecular mechanisms of carcinogenesis in different types of cancer." (PMID 36837670, 2023). "The secreted CTGF by cancer cells stimulated the CAF infiltration to form a stiffened collagen‐enrichment microenvironment, thus activating PIEZO1 to form a positive feedback loop." (PMID 37983931, 2023). "Herein, we found that the DC mechanical sensor Piezo1 stimulated by mechanical stiffness or inflammatory signals directs the reciprocal differentiation of TH1 and regulatory T (Treg) cells in cancer." (PMID 35993548, 2022). "In particular, we discuss the roles of Piezo1/2, TRPC1, TRPC5, TRPM2, TRPM4, TRPM7, TRPV2, and TRPV4 in mechanosensing and cancer metastasis." (PMID 36158191, 2022). "In the following section, we provide an overview of how Piezo1/2, TRPC1, TRPC5, TRPM2, TRPM4, TRPM7, TRPV2 and TRPV4 affect cancer cell behavior." (PMID 36158191, 2022). "Here, we further showed that Piezo1 targeting the calcineurin-NFAT axis modulates DC-derived polarizing cytokine production to direct Treg and TH1 cell differentiation in cancer." (PMID 35993548, 2022). "Next, we describe how Piezo1/2 and transient receptor potential (TRP) channels respond to these physical cues to regulate cancer cell behavior during different stages of metastasis." (PMID 36158191, 2022). "To test this, we used the clinically available anti-cancer agent Bortezomib (BTZ) and treated Piezo1−/− HEK293T which overexpressed the G2029R mutant with concentrations that ranged from 0.1–10 nM." (PMID 34867393, 2021). "This reduction in mesenchymal-promoting genes supports the role that Piezo1 plays in EMT and, therefore, cancer cell dissemination." (PMID 34831037, 2021). "Piezo1 expression was confirmed in COLO 205, DU145, and MDA-MB-231 cancer cell lines to determine if Yoda1-TRAIL sensitization occurs in other cancer cell lines." (PMID 31685811, 2019). "The mRNA (E,F) and protein (G,H) expression of PIEZO1 and PIEZO2 in cancer tissue from NSCLC patients were significantly lower than that in the adjacent non-cancer tissues." (PMID 30745454, 2019). "Knocking down PIEZO1 expression reduced SW982 cell-viability as well as Yoda1-induced Ca2+ response, suggesting that PIEZO1 is a potential regulator of cancer cell-viability." (PMID 29757938, 2018). "In glioma, ECM stiffening creates a mechanical microenvironment that activates Piezo1, which in turn promotes focal adhesion assembly and stimulates the integrin-FAK signalling pathway, thereby promoting cancer cell proliferation, migration and further stiffening." (PMID 41437911, 2026). "To clarify how the downregulated Piezo1 channel contributes to stiff substrate-induced increase in A549 cell migration, we focused on filopodium formation, due to its implication in probing ECM stiffness and directing cancer cell migration." (PMID 41585435, 2026). "The influx of calcium ions through Piezo1 channels has been identified as a trigger for calpain 2-dependent apoptosis via the BAX protein, leading to the mitochondrial activation of caspase 3, which is a key mechanism in the cancer response." (PMID 40727658, 2025). "Our research shows that PIEZO1 expression is positively correlated with key immune checkpoints, including CD274 (PD-L1), CTLA4, LAG3, PDCD1 (PD-1), PDCD1LG2 (PD-L2), and TIGIT across various cancer types." (PMID 40977743, 2025). "In summary, our findings indicated that ECM stiffness activated the Piezo1/ITGB1/YAP axis, which in turn further strengthened ECM accumulation and promoted cell proliferation, forming a positive feedback loop that drove the progression of cancer." (PMID 40667648, 2025). "Targeting the PIEZO1-m6A axis (e.g., using m6A inhibitor STM2457) could thus represent a novel combinatorial strategy against PIEZO1-driven cancers." (PMID 40977743, 2025).
cancer (continued). "Interestingly, PIEZO1 expression was significantly downregulated in KICH compared to normal tissue, contrasting with its oncogenic role observed in other cancers." (PMID 40977743, 2025). "This adhesion process is absent in transformed cancer cells, where growth appears independent of local Ca2+ entry at rigid matrix sites, and Piezo1 is decoupled from traction forces and adhesion signaling." (PMID 38534326, 2024). "Further analysis suggests that these worse survival outcomes may be due to increased aggressive cancer pathways, including epithelial–mesenchymal transition and hypoxia, along with decreased CD8+ and CD4+ T cell infiltration in high-PIEZO1 HR-negative tumors." (PMID 38398074, 2024). "Meanwhile, R11 peptides activated the Piezo1/YAP and Ca2+ signal by inducing mechanical fusion and morphological alterations in the membrane, further activating integrin β1 and improving peptides uptake efficiency in cancer cells." (PMID 39258781, 2024). "The CTGF secreted from cancer cells may orchestrate a CAF‐enriched microenvironment, thereby initiating a self‐perpetuating positive feedback loop via PIEZO1 activation." (PMID 37983931, 2023). "The mechano-signal transducers Piezo1, integrin and YAP are tightly involved in cancer immunity." (PMID 35331296, 2022). "Although previous studies have confirmed that Rab5c was an oncogene that promote cancer progression or chemoresistance through various pathways, but our research first illustrate that Rab5c act as a target of Piezo1 and activate TGF-β signaling through in cancer cells." (PMID 35461277, 2022). "More importantly, future research focused on Piezo1-mediated EMT in embryonic development, fibrosis and cancer progression might increase our knowledge of how mechanical force controls EMT." (PMID 35615675, 2022). "Despite above, there is no pancancer study exploring the correlation between PIEZO1 and different tumors, since most research studies involving PIEZO1 in tumors focus on one certain cancer." (PMID 35747124, 2022). "Therefore, extracellular calcium influx through Piezo1 upregulates PKA, ERK, Rac1, and ROCK activities which have the potential to promote cancer cell survival, proliferation, and migration." (PMID 35646889, 2022). "Recent studies have suggested that Piezo1 is involved in regulating many of diseases, including the infectious inflammation and cancer." (PMID 35993548, 2022). "However, within the same study, the overexpression of Piezo1 reduced VEGF expression, further implicating the dynamic role of Piezo1 in VEGF expression and cancer metastasis." (PMID 34831037, 2021). "While Piezo1 has not always been explored in the context of cancer, its role in blood vessel growth is evident." (PMID 34831037, 2021). "However, the relationships remain unknown among the Piezo1 channel, [Ca2+]i, CaN, SSH, cofilin phosphorylation and filopodia formation in cancer cell migration, especially in substrate stiffness regulation of cell migration." (PMID 41585435, 2026). "However, in cancer cells, Piezo1 fails to localize to adhesions and has little effect on adhesion turnover, suggesting a tumour-associated functional shift." (PMID 40806720, 2025). "Notably, cyclic stretch enhances the expression of Piezo1 in cancer cells but does not have the same effect on epithelial cells." (PMID 40727658, 2025). "Similarly, the Piezo1–YAP axis in CAFs is activated under high mechanical tension, stimulating the secretion of collagen, fibronectin (FN), TGF-β, and interleukin-6 (IL-6), which in turn promotes ECM fibrosis and further enhances cancer cell invasion." (PMID 40821847, 2025). "In addition, we showed that PIEZO1 is correlated with EMT, hypoxia, and TGF-β signaling, processes which have all been shown to be correlated with decreased CD8+ and/or CD4+ T cell infiltration in various cancer types." (PMID 38398074, 2024).
cancer (continued). "When internalized by NSCs, MNBs activate Piezo1 channels, leading to Ca2+ influx, which activates the expression of BMP2 and increases the phosphorylation of SMAD, adjusting the expression of differentiation genes to prevent NSCs from expressing genes that promote cancer." (PMID 39539343, 2024). "Our enrichment results suggest that the PIEZO1 ion channel may respond to mechanical forces to induce cellular junction deregulation, cytoskeletal remodeling, and TME modulation, thus promoting EMT and the motility of cancer cells." (PMID 38398074, 2024). "Piezo1 allows cancer cells without restriction to continue multiplying, regardless of whether they get away with contact inhibition." (PMID 36615408, 2022). "Lamin-A, C profiles appear strikingly similar to those for the mechanosensitive factors Vinculin, Yap1, and Piezo1, whereas datasets for lamin-B1 align with and predict regulation by the cell cycle transcription factor, FOXM1, and further predict poor survival across multiple cancers." (PMID 35719698, 2022). "Our research showed that Piezo1 activated TGF-β signaling which has not been reported, indicated Piezo1 might be a regulator of multi signaling pathways, and functioning through different pathways in various types of cancers." (PMID 35461277, 2022). "In this work, we adopt a diversity of databases such as The Cancer Genome Atlas (TCGA), Genotype Tissue-Expression (GTEx), cBioPortal, Gene Ontology (GO) and Kyoto Encyclopedia of Genes and Genomes (KEGG) to assess the expression levels of PIEZO1 and the link with survival in various tumors." (PMID 35747124, 2022). "However, whether and how Piezo1 channels mediate compression-enhanced invasive phenotype of cancer cells has not been examined." (PMID 34979904, 2022). "To test whether the compression-enhanced cancer cell invasion was mediated through SACs or more specifically through Piezo1, we pretreated the MDA-MB-231 cells with either Gd3+ (non-specific SACs inhibitor), or GsMTx4 (more specific Piezo1 inhibitor), followed by exposure to compression at 400 Pa." (PMID 34979904, 2022). "Several genes with recurrent mutations were likely chance events, enhanced by their large size: DNAH11 (4516aa), TTN (34350aa), PIEZO1 (2521aa), TRPM6 (2022aa); none are thought to be involved in the pathogenesis of any form of cancer." (PMID 30256787, 2018). "However, the role of Piezo1 in the mechanical control of EMT in other cell types, particularly cancer cells, has not been investigated to date." (PMID 35615675, 2022). "However, the relationship between Piezo1/ITGB1 and ECM stiffness in cancer is not clear." (PMID 40667648, 2025).
infection (18 papers, 2018 to 2025). The state of being infected such as from the introduction of a foreign agent such as serum, vaccine, antigenic substance or organism. "PIEZO1 deficiency in innate cells markedly reduced pulmonary inflammation in infection and fibrotic models." (PMID 41019411, 2025). "GSEA of Piezo1scKO MuSCs disclosed enhanced activity of the PKC signaling pathway, confirmed by higher enzyme activity of PKC in cultured MuSC, in which the floxed Piezo1 alleles were deleted by Ad-Cre infection." (PMID 35395625, 2022). "To this end, we measured ROS levels in MuSCs, in which the floxed Piezo1 alleles were deleted by Ad-Cre infection, either in the absence or presence of the Ca2+ chelator BAPTA-AM." (PMID 35395625, 2022). "Moreover, we observed a strong increase of apoptosis in cultured MuSC, in which the floxed Piezo1 alleles were deleted by Ad-Cre infection, based on TUNEL- and cleaved Casp3-staining." (PMID 35395625, 2022). "Moreover, repeated peripheral infection at 8, 11, 14, and 17 months of age caused a large increase in Piezo1 channels in the dentate gyrus of 18-month iTG rats (25 ± 8%) compared to their non-infected and age-matched TG counterparts." (PMID 30405400, 2018). "IECs sense infections via Piezo1, which detects infection-induced ruffles and mediates Ca2+ influx and ATP release, ultimately imitating acute inflammation." (PMID 39062518, 2024). "Here, we demonstrate in vitro that human red blood cell (RBC) infection by Plasmodium falciparum is prevented by the pharmacological activation of PIEZO1." (PMID 37071200, 2023). "In primary astrocytes derived from mice, some researchers use LPS to mimic the infection situation and observe an increase in PIEZO1 expression." (PMID 36765838, 2023). "A kidney-specific Piezo1-knockdown mouse model was successfully established by a 3-week AAV infection, and Yoda1 was then injected intraperitoneally for 17 days to stimulate Piezo1." (PMID 36471394, 2022). "To characterize the role of Piezo1 in innate immune cells upon infection, we prepared BMDMs from the Piezo1P1tdT transgenic mice and infected them with E. coli." (PMID 34112781, 2021). "How does Piezo1 regulate neutrophil NET formation during antivirus infection?" (PMID 39890818, 2025). "A growing body of evidence has shown that Piezo1 transduced mechanical force to myeloid cells (e.g. leukocytes, monocytes and macrophages) and served as a vital regulator of innate immune responses with implications for tumor immunity and pathogen infections." (PMID 38303078, 2024). "Similarly, an in vitro study showed that human RBC infection by P. falciparum strain invasion was efficiently suppressed by the pharmacological activation of Piezo1 with Yoda1 via RBC dehydration." (PMID 38303078, 2024). "In this study, taking advantage of an in vitro model of human RBC infection by P. falciparum, we aimed at exploring the antimalarial activity of PIEZO1 pharmacological activators and at determining which step of the infection cycle is PIEZO1 sensitive." (PMID 37071200, 2023). "Aging and infection can induce the upregulation of PIEZO1 in the plaque-induced reactive astrocytes, which may in turn trigger astrocyte proliferation." (PMID 36765838, 2023). "We then asked whether Piezo1-dependent calcium influx induces the activation of Mst1/2-Rac1 axis during the infection." (PMID 34112781, 2021). "However, DG Piezo1 expression showed a moderate correlation with GFAP intensity in 18-month iWT rats exposed to repeated peripheral infections (Pearson r = 0.523, p < 0.0001)." (PMID 30405400, 2018). "However, Piezo1 expression in the audiovisual cortex did display significant upregulations (21 ± 3%) in 18-month iTG rats in response to repeated peripheral infections." (PMID 30405400, 2018).
infection (continued). "Piezo1, as a key protein that allows immune cells to receive mechanical signals and convert them into chemical signals, can sense the mechanical stress of NPWT and regulate immune response reactions in the local immune microenvironment of infections." (PMID 40529353, 2025). "Finally, Piezo1 expression in the DG displayed very strong correlations with Aβ1-42 fluorescence intensity in 12- and 18-month TgF344-AD rats either with or without peripheral infection." (PMID 30405400, 2018).
cardiovascular diseases (14 papers, 2021 to 2026). "Together, our study highlights an important role for Piezo1 and its respective mutations in macrophage mechanosensing, lipid uptake, and cardiovascular disease." (PMID 39544498, 2024). "It is plausible that while socioeconomic, underlying disease, and lifestyle are often implicated, genetic mutations to the Piezo1 channel could also contribute as a risk factor in cardiovascular disease." (PMID 39544498, 2024). "PIEZO1 is expected to become an emerging target for the prevention and treatment of cardiovascular diseases." (PMID 39272994, 2024). "In cardiovascular diseases, Piezo1’s role in autophagy regulation has also been established." (PMID 41507149, 2026). "Additionally, we explore a range of PIEZO1 chemomodulators and their therapeutic potentials in cardiovascular diseases." (PMID 39272994, 2024). "However, besides the research on oncology and cardiovascular diseases, there are very few studies on the function of PIEZO1 in bone-related diseases." (PMID 35563641, 2022). "Moreover, stiffness measurements, characterization of receptor expression of explanted aortas and in vivo cholesterol modulation, as well as detailed mechanistic studies will provide more insight into Piezo1-mediated molecular pathways involved in cardiovascular disease." (PMID 39544498, 2024). "However, when activated by pathological factors or aberrantly expressed, PIEZO1 may contribute to various cardiovascular diseases." (PMID 39272994, 2024). "Therefore, further understanding of PIEZO1 mechanisms may point to unique ways of lowering triglycerides and cholesterol, thus protecting against cardiovascular disease." (PMID 39331703, 2024). "Therefore, future studies that include targeted deletion of this mechanosensor in preadipocytes and other PVAT cells that take into account sex differences in normotensive and hypertensive animals are required to determine the impact of PIEZO1 on cardiovascular diseases." (PMID 36120469, 2022). "However, it is unknown if PVAT preadipocytes express Piezo1, how PIEZO1 activation alters PVAT adipogenic and lipogenic responses, and if PIEZO1 activity could be a mechanism triggering PVAT remodeling during cardiovascular diseases." (PMID 36120469, 2022). "However, identification and functional chacterization of both Piezo1 and TRPV4 throughout the vascular endothelium would be needed before considering therapeutics for cardiovascular diseases directed against these ion channels." (PMID 33298523, 2021).